BCAT1 (branched chain amino acid transaminase 1)
Diseases named in the same sentence as BCAT1 in open-access papers (continued):
Sharing a sentence is not in itself a finding about the gene and the disease.
breast carcinoma (continued). "In breast cancer, BCAT1 and BCKDH are upregulated, enhancing BCAA metabolism and leading to increased substrates for the TCA cycle." (PMID 34354601, 2021). "The expression of BCAT1 is usually upregulated in diverse cancers, such as ovarian cancer, breast cancer, and GC." (PMID 32855634, 2020). "Compared with those in normal breast tissue, BCAT1 levels have been shown to be elevated in various breast cancer tissues, including in invasive carcinoma, intraductal carcinoma, and lobular carcinoma." (PMID 32571264, 2020). "The BCAAs levels of plasma and tissue are increased in breast cancer, which is accompanied by the elevated expression of BCAT1." (PMID 29570613, 2018). "BCAT1 expression also contributed to the growth of breast cancer cell lines and appeared to act through mTORC1 activity." (PMID 29211698, 2018). "The authors found that BCAAs were increased in patients with breast cancer (compared with healthy controls), in both peripheral blood serum and cancer tissue, and BCAT1 was also overexpressed." (PMID 29211698, 2018). "Zhang and Han also found BCAT1 expression promoted mTOR activity, but in the context of breast cancer cells." (PMID 29211698, 2018). "Conversely, BCAT1 knockdown can reduce breast cancer cell growth and migration in vitro." (PMID 41502503, 2025). "From this evidence, BCAT1 overexpression leads to breast cancer progression." (PMID 40507232, 2025). "With the inhibition of BCAT1 and doxycycline usage, the growth of breast cancer cells is inhibited." (PMID 40507232, 2025). "Increased expression of BCAT1 has been involved in promoting the development of breast cancer." (PMID 40075737, 2025). "For instance, BCAT1, by enhancing mitochondrial biosynthesis and function through mTOR mediation, may stimulate breast cancer cell growth." (PMID 38309289, 2024). "BCAT1 also can induce the mTORC1 pathway to amplify mitochondrial biogenesis and generate ATP, providing energy and enhancing tumor cells’ growth and colony formation in breast cancer." (PMID 37637065, 2023). "BCAT1 knockdown may help reduce mTOR signaling and reduce the growth rate of breast cancer cell lines." (PMID 38028625, 2023). "Indeed, BCAT1 levels have been shown to be elevated in various breast cancer tissues (including invasive carcinoma and intraductal carcinoma) as compared with normal breast tissue." (PMID 35299741, 2022). "In addition, expression of BCAT1 activates mTORC1 signaling to increase mitochondrial biogenesis and ATP production contributing to growth and colony formation of breast cancer cells." (PMID 34354601, 2021). "BCAT1 knockdown resulted in blunted growth of breast cancers." (PMID 34354601, 2021). "Overexpression of BCAT1 shows that BCAAs catabolism is activated in human breast cancer, and opposing results are observed that the knockdown of BCAT1 can inhibit breast cancer cell growth by activating the mTOR, but not AMPK or SIRT1, signaling mediating mitochondrial biogenesis and function." (PMID 29570613, 2018). "Here, BCAT1 controlled cell cycle progression, sustaining breast cancer proliferation." (PMID 29211698, 2018). "Intriguingly, BCAT1 may also contribute to a cancer stem cell phenotype in breast cancer." (PMID 41502503, 2025). "Thus, in these tumors, BCAT1 knockdown may contribute to reduced mTOR signaling and, as a consequence, a decreased growth rate of breast cancer cell lines." (PMID 35409380, 2022). "For example, interferon gamma (IFNγ) released by T cells has been reported to increase cancer stemness in breast cancer via nuclear factor kappa-B (NF-κB)/LAT1 pathway, and co-inhibition of LAT1 and BCAT1 reduced this effect." (PMID 41502503, 2025). "BAY-069, targeting both BCAT1 and BCAT2, has exhibited significant antiproliferative effects on glioblastoma cells and breast cancer cells." (PMID 39143065, 2024). "High expression of BCAT1 and BCKD genes in breast cancer activates mTOR signaling, and BCAA catabolism is enhanced." (PMID 38028625, 2023).
breast carcinoma (continued). "Regardless, high BCAT1 expression corresponds with increased tumor aggressiveness and has been reported to be a potential prognostic marker in TNBC breast cancer as well as other malignancies including colorectal cancer." (PMID 34638293, 2021). "The expression of BCAT1 is also upregulated in hepatocellular carcinoma (HCC), breast cancer, and NSCLC, and indicates a poor prognosis." (PMID 34976806, 2021). "PE‐Lap (FBP1, ITGA11, TRIM68, BCAT1, ZNF780A, UTP20 and GRB7) predicted outcomes of breast cancer patients treated with lapatinib." (PMID 34766125, 2020). "BCAT1 is one DOT1L target gene regulated by H3K79 methylation and is responsible for DOT1L-mediated cell migration in breast cancer cells." (PMID 32042335, 2020). "BCAT1 is upregulated and functionally required for several malignancies including glioblastoma, hepatocellular carcinoma (HCC), colorectal and breast cancers, and chronic myelogenous leukemia." (PMID 30265706, 2018). "BCAT1 (branched chain aminotransferase 1 gene, also known as ECA39) is also significantly up-regulated in Burkitt’s lymphoma and breast cancer." (PMID 23758864, 2013). "BCAT1 expressed in the cytoplasm was highly expressed in human epidermal growth factor receptor 2 positive (HER2+) breast cancer, while BCAT2 expressed in the mitochondria tended to be highly expressed in estrogen receptor-positive (ER+) breast cancer." (PMID 37699892, 2023). "Within the context of breast cancer, subtype specific expression of BCAT enzymes has been observed with the cytosolic isoform BCAT1 commonly expressed in breast tumors that lack estrogen receptor or ER-activity, including progressive HR+ tumors that have lost estrogen dependency." (PMID 34638293, 2021). "Thus, it has been shown that the expression of BCAT1, which is regulated by the DOT1L histone methyltransferase, promoted the migrations of breast cancer cells." (PMID 32571264, 2020). "While it is not clear if BCKDK has been proposed to be involved in breast cancer cell metastasis via regulation of BCAT1 activity, it is of great interest to further investigate the relationship between BCKDK and BCAT1 in breast cancer development." (PMID 37460470, 2023).
glioblastoma (36 papers, 2015 to 2025). The most malignant astrocytic tumor (WHO grade IV). "Of the two isoforms, BCAT1 is the major enzyme implicated in cancer growth and is highly expressed in various cancers including glioblastoma (GBM) and ovarian cancer." (PMID 32824193, 2020). "Mutations in either IDH1 or IDH2, commonly seen in glioblastomas, contribute to downregulation of BCAT1 through DNA methylation of the BCAT1 promoter and the corresponding epigenetic silencing of BCAT1." (PMID 29211698, 2018). "The study found that BCAT1 is phosphorylated by BCKDK in glioblastoma, which enhances its activity and stability while inhibiting its degradation mediated by STUB1 ubiquitination, thereby promoting tumor growth." (PMID 40438606, 2025). "LAT1 is a transporter of BCAAs, and studies have found that hypoxia upregulates the mRNA and protein levels of LAT1 and BCAT1 in human glioblastoma (GBM) cell lines through the binding of HIF-1α and HIF-2α to the intron of the BCAT1 gene." (PMID 40438606, 2025). "This interest is largely driven by the frequent overexpression of BCAT1 observed in glioblastoma, highlighting its potential role in tumor metabolism and progression." (PMID 40507232, 2025). "The glutamate-synthesizing aminotransferase BCAT1 (produces glutamate from α-ketoglutarate) may overproduce glutamate in tumors and an upregulation of BCAT1, that may in part be driven by hypoxic conditions of fast-growing glioblastoma, was associated with poor patient survival." (PMID 38835368, 2024). "For instance, BCAT1, which is highly expressed in glioblastoma, has been found to promote tumor growth." (PMID 39668829, 2024). "Numerous studies have established a correlation between elevated BCAT1 expression in tissues and the development of various cancers, such as glioblastoma, radiation-induced breast cancer, acute myeloid leukemia, and gastric cancer." (PMID 38309289, 2024). "Expression of Forkhead box protein M1 (FOXM1), a downstream target of HIF-1α39 that has been shown to play multiple roles in glioblastoma, was downregulated following BCAT1 knockdown and this was accompanied by downregulated expression of its target genes." (PMID 37885806, 2023). "There is a wide variation in BCAT1 expression in glioblastoma and its role in proliferation and invasion is dependent on tumor subtype." (PMID 37885806, 2023). "Examination of the TCGA dataset for IDH wild-type glioblastoma also showed a wide variation in the expression levels of BCAT1, with A11 representative of tumors with high expression and S2 tumors with low expression." (PMID 37885806, 2023). "The aim of this study was to determine the role of BCAT1 in driving the proliferation and invasion of glioblastoma cells and xenografts that have widely differing levels of BCAT1 expression and the mechanism responsible." (PMID 37885806, 2023). "The activity of BCAT1 was modulated in IDH wild-type patient-derived glioblastoma cell lines, and in orthotopically implanted tumors derived from these cells, to examine the effects of BCAT1 expression on tumor phenotype." (PMID 37885806, 2023). "Noncoding RNAs have been widely studied in recent years, glioblastoma is also regulated by competitive endogenous RNA, circVPS18 accelerates the progression of glioblastoma through miR-1229-3p/BCAT1, providing a potential therapeutic target for glioblastoma." (PMID 38028625, 2023). "IDH wild-type patient-derived (A11, S2, SP20, and A25) and established human (U87 and U251) and rat (C6) glioblastoma cell lines showed variable concentrations of BCAT1 and BCAT2." (PMID 37885806, 2023). "Among the genes studied, PER showed a transcriptional effect in glioblastoma cells by increasing the expression of BCAT1 and GLUL." (PMID 36831869, 2023). "Upregulation and functional requirements of BCAT1 have been reported for glioblastoma, colorectal tumours, and myeloid leukaemia." (PMID 37076565, 2023).
glioblastoma (continued). "DNA methylation at BCAT1’s promoter inhibits transcription, which is linked to BCAT1 downregulation in isocitrate dehydrogenase (IDH) mutant anaplastic astrocytoma and glioblastoma." (PMID 36358687, 2022). "HIF-1 has been shown to upregulate both the mRNA and protein levels of BCAT1 in human glioblastoma cell lines and primary glioblastoma spheres in hypoxia circumstances." (PMID 36358687, 2022). "Glioblastoma cells overexpress branched chain amino acid transaminase 1 (BCAT1) which enhances excretion of branched chain ketoacids (BCKA) through MCT1 that influx into nearby macrophages and reduce their phagocytic ability." (PMID 34277624, 2021). "The suppression of BCAT1 can block glutamate excretion and, thus, leads to reduced growth and invasiveness of glioblastoma." (PMID 33511116, 2020). "In IDH1 mutant glioblastoma, BCAT1 is transcriptionally suppressed because of the hypermethylation of three CpGs in the promoter, and this is also the consequence of IDH1 mutation-induced 2-hydroxyglutarate (2-HG)." (PMID 33511116, 2020). "For example, suppression of BCAT1 in U-87MG, a human primary glioblastoma cell line, produced smaller tumors in mice." (PMID 29211698, 2018). "BCAT1 expression in glioblastoma tumors is specific to those carrying wild-type isocitrate dehydrogenase 1 and 2 (IDH1 and IDH2)." (PMID 29211698, 2018). "Excitingly, a clinical trial (NCT05664464) is ongoing, using a combination of gabapentin with a compound to inhibit glutamate secretion and receptor activation in conjunction with radiotherapy to explore the effectiveness of BCAT1 inhibition in glioblastoma patients." (PMID 40507232, 2025). "Glioblastoma cells highly express BCAT1, which initiates the catabolism of BCAAs." (PMID 38305803, 2024). "Glioblastoma cells also synthesize large amounts of the excitatory neurotransmitter glutamate from α-ketoglutarate via branched chain amino acid transaminase-1 (BCAT-1) which is released into the tumor microenvironment at high concentrations via the glutamate-cystine antiporter system xc." (PMID 38225589, 2024). "To sum up, we identified seven genes (GRIA1, GRIA2, GRIK1, GRIK4, GRM3, GLUL, BCAT1) whose mRNA expression may serve as potential molecular biomarker candidates to distinguish glioblastoma and brain metastases tissue derived from surgical resections." (PMID 38835368, 2024). "In isocitrate dehydrogenase 1 (IDH1) wildtype glioblastoma, branched chain amino acid transaminase 1 (BCAT1) is also often upregulated and may contribute to a glutamatergic phenotype." (PMID 38835368, 2024). "Inhibiting BCAT1 in a human primary glioblastoma cell line produced smaller tumours in mice." (PMID 38369471, 2024). "In summary, increased expression of BCAT1 in glioblastoma cells with preexisting high levels of expression leads to a decrease in α-KG concentration, stabilization of HIF-1α, and increased cell proliferation and invasion mediated by HIF-1α-dependent expression of FOXM1." (PMID 37885806, 2023). "However, examination of the Cancer Genome Atlas (TCGA) data shows that there are a wide variation in BCAT1 expression in IDH wild-type glioblastoma." (PMID 37885806, 2023). "Indeed, upregulation of BCAT1 is reported in glioblastomas, HCC, leukemias, osteosarcomas, ovarian and endometrial cancer." (PMID 34526485, 2021). "Emerging data has demonstrated a critical role for BCAT1 in glioblastoma growth." (PMID 33493139, 2021). "In addition, the data from GSE16011, GSE4290, REMBRANDT, TCGA and CGGA datasets reconfirmed our previous findings and detailed that BCAT1 is preferentially expressed in classical and mesenchymal subtype and less expressed in proneural subtype glioblastoma." (PMID 33493139, 2021). "Therefore, BCAT1 represents a potential therapeutic target and useful prognostic factor for glioblastoma patients." (PMID 33493139, 2021).
glioblastoma (continued). "Moreover, increased extracellular secretion of BCKAs in a BCAT1 dependent manner supports cell proliferation in PDACs and survival of glioblastoma cells by evading immune surveillance." (PMID 34526485, 2021). "Moreover, the isoform BCAT1 has been proposed as a prognostic marker of glioblastoma, ovarian cancer, breast cancer, hepatocellular carcinoma, and chronic myelogenous leukemia (CML)." (PMID 32238881, 2020). "Similarly, knockdown of BCAT1 expression (or pharmacological BCAT1 inhibition) in glioblastoma cells reduced the formation of glutamate." (PMID 29211698, 2018). "Moreover, shRNA-directed knockdown of IDH1 led to strong downregulation of BCAT1 expression in glioblastoma cell lines." (PMID 26372729, 2015). "In addition, BCAT1 knockdown can strongly restrict tumor growth and progression in glioblastoma." (PMID 33493139, 2021). "Branched-chain aminotransferase 1 (BCAT1) has been proposed to drive proliferation and invasion of isocitrate dehydrogenase (IDH) wild-type glioblastoma cells." (PMID 37885806, 2023). "High expression of BCAT1 is a marker for predicting poor prognosis in IDH1 wild-type glioma patients, providing an important target site for glioblastoma patients." (PMID 38028625, 2023). "Compared to other tumors, glioblastoma (GBM) owns one of the highest levels of BCAT1 expression." (PMID 33493139, 2021). "Lastly, 48 h exposure of hypoxia has been shown to increase both mRNA and protein levels of L-type amino acid transporter 1, a branched-chain amino acid (BCAA) transporter, and branched-chain aminotransferase 1 (BCAT1), which catalyzes the first step in BCAA catabolism, in glioblastoma cells." (PMID 39914740, 2025). "BCAT1 overexpression, however, is evidently not universally essential for glioblastoma cell growth and invasion as indicated by the analysis of the TCGA dataset and the results obtained here with S2 cells." (PMID 37885806, 2023). "Specifically, BCAT1 expression is dependent on the concentration of α-ketoglutarate (α-KG) substrate and could be suppressed by downregulation of IDH1 in glioblastoma cell lines or overexpression of mutant IDH1 in immortalized human astrocytes." (PMID 33493139, 2021). "Recent studies were indicative for the important role of BCAT1 in the progression of several malignancies, including medulloblastomas, nonseminomas, colorectal and nasopharyngeal carcinomas and glioblastomas." (PMID 26372729, 2015). "BCAT1 expression could be suppressed by ectopic overexpression of mutant IDH1 in immortalized human astrocytes and suppression of BCAT1 significantly reduce tumor growth in a glioblastoma xenograft model." (PMID 33072547, 2020). "First, we compared glioblastoma and metastasis cells, and we could confirm that metastasis cell cultures expressed significantly less BCAT1, EAAT2 and SLC7A11 as compared to glioblastoma cells suggesting that these genes may represent a glioblastoma-typical gene profile." (PMID 30716120, 2019). "Similarly, a recent work on glioblastoma (GBM) revealed that HIF-1α fosters branched-chain amino acid (BCAA) metabolism by upregulating the expression of both BCAA transporter LAT1 and BCAA metabolic enzyme BCAT1." (PMID 32932943, 2020). "Following 48 h of incubation with two different doses of anticonvulsants, significant effects could only be found in the expression of BCAT1, EAAT2 and GLUL in glioblastoma cells, whereas no changes in IDH1 and SLC7A11 expression were found." (PMID 30716120, 2019).